IL2 (interleukin 2)
Diseases named in the same sentence as IL2 in open-access papers (continued):
Sharing a sentence is not in itself a finding about the gene and the disease.
hematologic malignancies (20 papers, 2012 to 2026). "Spike stimulation increases IL-2 levels in patients with hematological malignancies, but the IFN-γ and tumor necrosis factor α (TNF-α) remain lower, which indicates a reduced magnitude of protection by T cell response." (PMID 36851363, 2023). "When combined with low doses of interleukin-2 (IL-2) as co-treatment, BrHPP even demonstrated strong potential in specific activation of Vγ9Vδ2 T cells in clinical trials for the treatment of hematological malignancies and solid tumors." (PMID 36771066, 2023). "Related work has focused on the application of IL‐2 during haplo‐identical NK cell infusion treatment for hematologic malignancy." (PMID 32480431, 2020). "When daily IL‐2 treatment was used as part of an autologous γδT cells transfer protocol in a small group of people with advanced hematologic malignancy, 3 out of 4 achieved complete remissions lasting between 2 and 8 months." (PMID 32480431, 2020). "IL-2- and IL-15-expanded NK cells, which were previously tested in clinical trials for hematological malignancies, showed similar moderate but statistically significant increases in CD107a expression induced by AMP-B at the same concentrations." (PMID 28608807, 2017). "In a fourth trial, four patients with advanced hematological malignancies received haploidentical transplants highly enriched for Vγ9Vδ2 T cells, followed by in vivo administration of Zoledronate and IL-2." (PMID 29163482, 2017). "Clinical studies demonstrated that transfer of ex vivo IL-2 expanded autologous NK cells alone or in combination with subcutaneous administration of IL-2 was safe and feasible in the treatment of solid tumors as well as hematological diseases." (PMID 34066067, 2021). "Thus, we designed a phase-I clinical trial evaluating the safety of a prophylactic donor-derived ex vivo IL-2 activated NK cell (IL-2 NK) infusion after allo-HSCT for patients with hematologic malignancies." (PMID 34071607, 2021). "The results of this study further indicate that cell culture without IL-2 addition was associated with higher clinical response rates in patients with solid and hematologic malignancies." (PMID 30621018, 2019). "A single infusion of allogeneic Vγ9Vδ2 T-cells, expanded ex vivo with ZOL plus IL-2, is being administered in a clinical trial (NCT03533816) to maximize antitumor response and reduce GvHD, after allogeneic hematopoietic cell transplant (alloHCT) and cyclophosphamide for hematologic malignancies." (PMID 35784326, 2022). "Therefore, T cell responses are more robust in patients with hematological malignancies; they can be detected in 34% to 75% of patients in whom serological response is negative (although 34% of seronegative individuals had CD4 responses with mainly IL-2-only monofunctional cells)." (PMID 36851363, 2023).
kidney (16 papers, 1998 to 2024). "Tacrolimus is an immunosuppressant responsible for inhibiting T-lymphocyte signal transduction as well as interleukin-2 (IL-2) transcription and is one of the most common immunosuppressive drugs administered to kidney transplant recipients." (PMID 35874759, 2022). "However, the CR kidney transplant patients had significantly elevated levels of proinflammatory cytokines IL-2 (P = 0.005), IL-1β (P = 0.05), and IL-6 (P = 0.05)." (PMID 24741575, 2014). "Also, our study revealed that to determine whether kidney patients have a T cell response, detection of IL-2 after specific stimulation is more sensitive than IFN-γ." (PMID 37198189, 2023). "Upon analysis, expression of the cytokines IFNB1, IFNG (IFN-γ), TNF (TNF-α), TGFB1 (TGF-β), IL1B, IL2, IL6, CXCL8 (IL-8), and IL10 were all significantly increased in ‘mesenchymal’ lung ADC compared to ‘epithelial’ tumors." (PMID 29440769, 2018).
renal disease (13 papers, 2014 to 2025). "This study aims to test the correlations between ROS, SOD3, IL-2, IL-6, and IL-18 and the first kidney disease-related hospitalization or death events in ESRD patients undergoing regular hemodialysis." (PMID 35740095, 2022). "In this study, we aimed to elucidate the correlation between different potential predictors (ROS, SOD3, hs-CRP, IL-2, IL-6, and IL-18) and first nephropathy-related hospitalization or death in ESRD patients receiving hemodialysis." (PMID 35740095, 2022). "Blood samples from all participants were collected for ROS, SOD3, IL-2, IL-6, and IL-18 measurement at the beginning of the study, and every kidney disease-related admission or death was recorded for the next year." (PMID 35740095, 2022). "Additional studies were conducted with anti-CD2 antibody-coated NPs loaded with only IL-2 revealed that these NPs had equivalent protective effects on the renal disease as NPs containing both IL-2 and TGF-β." (PMID 34211471, 2021). "Interleukin, the multifunctional inflammatory cytokines are closely associated with various renal diseases and the injury of kidney residential cells, such as IL-6, CXCL8, IL-1β, IL-2 and IL-4." (PMID 32765640, 2020). "The second limitation is relative to the advanced state of renal disease that may have reduced the potential effects of IL2 therapy." (PMID 26413873, 2015). "Patient characteristics, including sex, age, body mass index (BMI), etiology of primary renal disease, basic monthly biochemical data, ROS, SOD3, IL-2, IL-6, and IL-18, were analyzed." (PMID 35740095, 2022). "In addition, levels of IL-1α, IL-1β TNFα, INFγ, IL-2 and IL-10 were elevated in the sera of CKD compared to sham, suggesting that the chronic state of renal disease affects the inflammatory network." (PMID 29889834, 2018). "Interestingly, it has been demonstrated that various pro-inflammatory cytokines, including tumor necrosis factor-α (TNF-α), Interleukin-2 (IL-2), and transforming growth factor-β1 (TGF-β1), could induce endothelial cells into myofibroblasts in renal diseases." (PMID 37288756, 2023).
adenocarcinoma (12 papers, 1989 to 2026). A common cancer characterized by the presence of malignant glandular cells. "It is hypothesised that an increase in the abundance of Chryseobacterium in recurrent lung samples following the resection of early-stage adenocarcinoma is positively correlated with an upregulation of IL-2, IL-3, and IL-17 in the host transcriptome." (PMID 40357400, 2025). "IL-2 and IL-10 increased in mice that received untreated A549 cells, suggesting that the immune system mounts a regulated response against adenocarcinoma, which did not occur with A549NED cells." (PMID 36674504, 2023).
cardiovascular disease (12 papers, 2016 to 2026). "As propranolol is used in cardiovascular diseases for long time period, the drug concentration used in patients might be enough for inhibiting of inflammatory cytokines such as IL-2 and IFN-γ in vivo." (PMID 27252810, 2016). "We demonstrated that the non-traditional cardiovascular risk factors, the TG/HDL ratio, IL-2, IL-6, IL-17A, and INF-γ, were significantly increased in children with MetS than those without MetS, and may therefore be used as biomarkers to predict future cardiovascular disease." (PMID 37892418, 2023). "As the current analysis addressed baseline IL-2 in patients without cardiovascular disease, our results indicate IL-2 is a suboptimal and chronic inflammation component." (PMID 35568817, 2022). "Expanding atheroprotective Treg numbers through IL-2 may be a viable therapy; however, no data exists if this protects against cardiovascular disease, as expanded Tregs may result in increased exTreg numbers as well." (PMID 37681883, 2023). "We demonstrated that the TG/HDL ratio, IL-2, IL-6, IL-17A, and INF-γ were significantly greater in subjects with MetS than in those without MetS, and may therefore be used as biomarkers to predict future cardiovascular disease." (PMID 37892418, 2023).
neurological disorders (11 papers, 2012 to 2025). "Similarly, the IL-2-mediated expansion of peripheral Tregs in humans and mice has demonstrated efficacy in various neurological disorder models, including amyotrophic lateral sclerosis." (PMID 40804450, 2025). "In these neurological disorders, pro-inflammatory markers such as TNF-α, IL-1β, IL-2, INFγ, NOS, and ROS are increased according to postmortem brain samples." (PMID 38516464, 2024).
psychiatric disorder (10 papers, 2013 to 2025). A disorder characterized by behavioral and/or psychological abnormalities, often accompanied by physical symptoms. "The administration of IL-2 is in this setting an abrupt and higher dosage than the variations in low-grade inflammation seen in psychiatric disorders." (PMID 38549611, 2024). "A considerable body of evidence suggests that many neurological and psychiatric disorders are accompanied by disorders of IMs, like interleukin (IL)-1b, IL-2, IL-6, interferon (IFN), tumor necrosis factor a (TNF a), the soluble IL-6 receptor (sIL-6R), and the IL-1 receptor antagonist (IL-1RA)." (PMID 38674921, 2024). "Reduction of IL-2 levels in psychiatric disorders has been hypothesized to be a result of increase HPA axis activation via IDO (indoleamine 2,3-dioxygenase) mediated serotonin depletion and increased noradrenergic activity through the sympathetic nervous system." (PMID 35880170, 2022). "In addition to marked neurobehavioral effects, IL-2 impacts various psychiatric disorders." (PMID 23536796, 2013). "Incidentally, a clinical benefit of ld-IL-2 treatment in MDD will not only help alleviate the disease burden but also provide evidence of a direct contribution of the immune system (and Tregs) to psychiatric disorders." (PMID 29615964, 2018).
cardiac disease (9 papers, 2010 to 2024). "Of great interest are MMP-3 as a progression marker, MCP-3 as a urine marker, and IL-2 as a heart disease marker." (PMID 38476443, 2024). "In this review, the pathophysiological effects of interleukins including the IL-1 family (IL-1, IL-18, IL-33, and IL-37), IL-2, IL-4, the IL-6 family (IL-6 and IL-11), IL-8, IL-10, and IL-17 on primary cell types of heart disease is elucidated." (PMID 37047468, 2023). "In conclusion, additional experimental studies are needed to fully elucidate the role of IL-2 and develop its therapeutic potential in heart disease." (PMID 37047468, 2023). "This review will primarily focus on the pathophysiological effects of various interleukins including the IL-1 family (IL-1, IL-18, IL-33, IL-37), IL-2, IL-4, the IL-6 family (IL-6 and IL-11), IL-8, IL-10, IL-17 on primary cells of heart disease-CMs, FBs, ECs, and immune cells." (PMID 37047468, 2023). "Therefore, considering the significance of inflammation in cardiac diseases, the present study was designed to examine a sample of Iranian patients with CHF for the SNPs in IFN-γ gene at position +874 as well as IL-2 polymorphisms at positions −330 and +166." (PMID 30090212, 2018). "In CD, IFN-γ, IL-2, IL-6, IL-10, IL-12, and IL-17 are proposed as surrogate markers of cardiac disease (versus no disease) (9, –, 14)." (PMID 34479416, 2021).
neurodegenerative disease (9 papers, 2017 to 2025). A disorder of the central nervous system characterized by gradual and progressive loss of neural tissue and neurologic function. "This is interesting as IL-2 is produced by neurons and astrocytes, is important in brain development and normal brain physiology and has been implicated in neurodegenerative disease, cognitive dysfunction and has been linked to ASD." (PMID 29312285, 2017). "It has been shown that IL-2 level is positively correlated with a reduction in pathological protein aggregates in a new transgenic model of neurodegenerative disease (crossbreeding 5xFAD and Thy-Tau22 mice)." (PMID 40563933, 2025). "Notably, the study uncovered a close correlation between inflammatory pathways (such as IL-2, IL-8, IL-12) and pathways relevant to neurodegenerative diseases." (PMID 38919616, 2024). "In neurodegenerative diseases such as ALS, IL-2 exhibits dual effects." (PMID 40362746, 2025). "Strength training for 6-12 weeks did not alter plasma IL-1β, IL-2, IL-6 and TNF-α concentration in healthy elderly adults and patients with chronic-degenerative diseases, while 12 weeks of resistance training decreased muscle TNF-α mRNA in frail elderly individuals." (PMID 33936044, 2021).
gastrointestinal tumors (8 papers, 2011 to 2025). "The ethanol extract can improve the levels of serum TNF-α and IL-2 in mice, boost SOD activity, and decrease MDA content; thus, it can against the growth of digestive tumor cells with an inhibition activity of 68.84%." (PMID 39275063, 2024).
hematologic cancers (7 papers, 2015 to 2024). "Safety concerns such as capillary leakage syndrome 15 and influence on immune reconstitution after lymphodepletion during treatment of hematological cancer patients are additional shortcomings of IL-2 treatment." (PMID 37056568, 2023). "Several clinical trials were performed with IL-2 immunotherapy combined with histamine for solid neoplastic diseases and hematopoietic cancers with promising results." (PMID 35163302, 2022).
peripheral neuropathy (7 papers, 2013 to 2025). A disorder affecting the peripheral nervous system. "Because NAC prevents NF-kB activation, it suppresses the production of cytokines, including TNFα, IL-1β, and IL-2, which are important for the inflammatory pathway and the development of peripheral neuropathy." (PMID 41440136, 2025). "In painful peripheral neuropathies significantly higher blood levels of IL-2 mRNA and TNF-α mRNA were measured compared to healthy subjects." (PMID 23383716, 2013). "In our previous study, we reported that phytohemagglutinin (PHA)-induced interleukin-2 (IL2) mRNA levels in ex vivo whole blood obtained prior to bortezomib treatment could predict the incidence of bortezomib-induced peripheral neuropathy." (PMID 26115406, 2015).
blood cancer (5 papers, 2019 to 2025). "Furthermore, we found that 10 μM curcumin significantly enhanced the cytotoxicity of CAR T-cells against blood cancer cells while reducing cytokine secretion, including IFN-γ and IL-2." (PMID 40298832, 2025). "The expanded NK cells exhibit increased cytotoxic function against a panel of blood cancer and solid tumor cells as compared to IL-2-activated non-expanded NK cells." (PMID 31624330, 2019).
retinopathy (5 papers, 2012 to 2025). "IL-2, IL-10, IL-12, IFN-α, and TNF-α were unmeasurable in significantly more diabetic samples, and where measurable, the median levels were significantly lower in diabetic patients with and without retinopathy compared to non-diabetics." (PMID 22511846, 2012).
respiratory diseases (3 papers, 2014 to 2025). "Various cytokines, such as IL2, IL4, IL6, IL8, and TNFα, and other inflammatory markers, such as intercellular adhesion molecule (ICAM) 1, soluble P-selectin, and CRP, have previously been associated with metal exposure or respiratory diseases." (PMID 25272992, 2014).
central nervous system tumors (2 papers, 2013). "However, the elevation of endogenous IL-2 following MA TMZ may ultimately obviate the need for high-dose IL-2 administration, which is contraindicated in some patients with CNS tumors." (PMID 23527092, 2013).
head and neck tumor (2 papers, 2024). "In some preclinical studies, chemokines, cytokines, and other factors including lymphotoxin α (LTα), tumor necrosis factor-α and interleukin-2 were found that could induce the formation of TLS in head and neck tumor-bearing mice." (PMID 38583352, 2024).
metabolic disease (2 papers, 2021 to 2024). A congenital disorder (due to inherited enzyme abnormality) or acquired (due to failure of a metabolically important organ) disorder resulting from an abnormal metabolic process. "Based on these findings, we chose to treat PBMCs with HMGB1 in combination with IL-2 to reproduce a microenvironment similar to the inflammatory-related conditions potentially present in metabolic diseases such as T2DM." (PMID 34360753, 2021).
electrolyte imbalance (1 paper, 2014). "If diarrhea improves with delaying doses, IL-2 may continue, but if as a consequence of the diarrhea, the patient develops local pain and irritation and fluid loss and electrolyte imbalance are apparent holding another dose of IL-2 is prudent." (PMID 31546315, 2014).
musculoskeletal disorders (1 paper, 2022). "Other studies have shown that strenuous exercise negatively affects the immune system, such as IL-2 production and leukocyte responses and that increased physical activity increases the risk of musculoskeletal disorders." (PMID 35280221, 2022).
overlap syndrome (1 paper, 2017). "In the group of patients with overlap syndrome, as well as in a general group of AILD, but not in patients with AIH, levels of IL-2 were significantly lower compared to controls (2.07 (range 0.11–111.87) in patients with AILD compared to 2.76 (range 0.45–4.10); p < 0.05)." (PMID 28299346, 2017).
IL2 also shares sentences with these, for which no sentence is quoted: multiple myeloma (29 papers); chronic periodontitis (8); Kaposi's sarcoma (6); basal cell carcinoma (5); primary immunodeficiency (5); hypertriglyceridemia (4); Multiple Organ Failure (4); psoriatic arthritis (4); scleroderma (4); acute myocardial infarction (3); cardiac arrest (3); dermatomyositis (3); esophageal squamous cell carcinoma (3); generalized anxiety disorder (3); Hypofibrinogenemia (3); lower respiratory tract infection (3); Oral ulcer (3); pericarditis (3); Primary hypothyroidism (3); pulmonary hypertension (3); pulmonary sarcoidosis (3); unstable angina (3); vasculopathy (3); age-related macular degeneration (2); antibody deficiency (2); autoimmune enteropathy (2); Brain atrophy (2); brain inflammation (2); bronchiectasis (2); bronchitis (2).
A further 285 diseases each share a sentence with IL2 in 2 papers or fewer.